TIMP1 (TIMP metallopeptidase inhibitor 1)
Diseases named in the same sentence as TIMP1 in open-access papers (continued):
Sharing a sentence is not in itself a finding about the gene and the disease.
prostate carcinoma (continued). "Patients with prostatic cancer had higher levels of TIMP-1 and collagenase (P = 0.0001) and lower levels of TIMP-2 (P = 0.003) than controls." (PMID 8080738, 1994). "However, loss of TIMP1 and associated loss of PTEN promoted invasion and migration in prostate cancer in vivo, while TIMP1 overexpression was associated with cancer progression and poor prognosis in numerous clinical studies." (PMID 37313172, 2023). "To characterize senescent prostate cancer cells at single-cell resolution we collected the epithelial fraction of four prostate tumors from two different mouse models of prostate cancer, the Pten-null prostate conditional (Ptenpc−/−) and the Ptenpc−/−; Timp1−/− mouse models." (PMID 35449130, 2022). "In prostate cancer, NR2C2 could prevent or delay prostate tumorigenesis via regulating the ATM expression at the transcriptional level and could suppress prostate cancer invasion via altering the TIMP-1/MMP2/MMP9 signals." (PMID 34956884, 2021). "In addition, a similar pattern of uPA protein expression and an opposite increase in TIMP-1/2 mRNA and protein levels were observed in RC-58T/h/SA#4 primary prostate cancer cells and LnCaP prostate cancer cells, respectively, in the presence of O. japonica." (PMID 33567572, 2021). "The aims of this study were to clarify whether TIMP-1 expression is modified by miR-618 and to clarify the effect of miR-618 expression on the invasion of prostate cancer cells." (PMID 30340564, 2018). "Significant alterations in TIMP1 expression strongly suggests that altered proteinase activities could lead to formation of seminal protein fragments and could be a candidate for prostate cancer biomarkers." (PMID 28471417, 2017). "Whether detection of TIMP-1 UEA fucosylation in serum could help identify aggressive prostate cancer remained to be determined." (PMID 24015777, 2013). "To determine the TIMP-1 expression levels in human prostate cancer cells, we assembled a panel of human prostate cancer cell lines (LNCaP, VCaP, LAPC-4, 22RV1, DU145, PC3 and PC3/M), an immortalized normal prostate epithelial line (RWPE-1) and its malignant derivative (WPE1-NB26-65)." (PMID 24143225, 2013). "We measured TIMP-1 UEA fucosylation in sera of prostate cancer and found little UEA fucosyaltion." (PMID 24015777, 2013). "Interestingly, TSP-1 can regulate TIMP-1 production in human tumor cells, including those derived from prostate cancer." (PMID 23749112, 2013). "Moreover, docetaxel treatment, which is standard chemotherapy for prostate cancer, perpetrated TIS and exacerbated metastasis in TIMP1‐deficient cancer cells, but this reaction could be rescued with ABT‐263, thereby reducing metastatic events." (PMID 34137158, 2021). "In this study, stimulation of prostate cancer cells with apelin abolished TIMP2 expression by a greater extent than TIMP1 or TIMP3, suggesting that TIMP2 is more important than other TIMPs in apelin-mediated motility of prostate cancer cells." (PMID 36291151, 2022). "Our results indicated that the sonicated extract suppresses prostate cancer cell migration via the regulation of MMP-9 and TIMP-1." (PMID 36605288, 2022). "In this work, we have used CRISPR interference (CRISPRi) and CRISPR activation (CRISPRa) technologies to study the biologocal functions of ITGB5, TIMP1, and TMEM176B in prostate cancer cells." (PMID 34109215, 2021). "In this study, we used CRISPR interference (CRISPRi) and CRISPR activation (CRISPRa) technologies to regulate the transcription of ITGB5, TIMP1, and TMEM176B in prostate cancer cells." (PMID 34109215, 2021). "We found that most patients with prostate cancer overexpressed MMP-9; on the other hand, most of them underexpressed TIMP-1, RECK, and miR-338-3p." (PMID 35097136, 2021). "Through a series of cellualr experiments, we found that inhibition of ITGB5 or activation of TIMP1 and TMEM176B suppress prostate cancer." (PMID 34109215, 2021).
prostate carcinoma (continued). "Although ITGB5, TIMP1, and TMEM176B are abnormally expressed in several cancers, their molecular biological mechanisms in prostate cancer cells are still to be investigated." (PMID 34109215, 2021). "In prostate cancer survivors with history of radiation therapy, elevated levels of PAI 1, TIMP1, TIMP2, HGF and VEGF-A were detected in patients that received a radiation cystitis diagnosis." (PMID 33119677, 2020). "To further understand the function of TIMP-1 in prostate cancer, we studied the effect of recombinant-TIMP-1 (Rh-TIMP-1) on cell migration and invasion of prostate cancer cells." (PMID 28108731, 2017). "1,25D3 reduces prostate cancer cell invasion by suppressing the expression of MMP-9 and cathepsins and promoting the activity of tissue inhibitors of metalloproteinase-1 (TIMP-1)." (PMID 28947955, 2017). "This overview summarizes findings on the tissue and blood expression of MMPs, their function, regulation and prognostic implication in human prostate cancer, with a focus on MMP-2, -7, -9, MT1-MMP and tissue inhibitor of metalloproteinase 1 (TIMP-1)." (PMID 24978435, 2014). "Western blot was used to examine the TIMP-1, TIMP-2, MMP-2 and MMP-9 expressions in prostate cancer cells." (PMID 24475196, 2014). "Both experimental results showed that prostate cancer cell lines express various levels of TIMP-1 and that more malignant cell lines such as DU145, PC3 and PC3/M expressed higher levels of TIMP-1 at both mRNA and protein levels." (PMID 24143225, 2013). "The expression in prostate cancer of several MMPs and TIMPs, such as MMP-2, -7, -9, -13 and -14, TIMP-1, -2 and -3, has been recently reported." (PMID 20160732, 2010). "For example, urinary elevations of fibrotic mediators (PAI-1, TIMP-1/2) and angiogenic factors (VEGF-A) observed in prostate cancer survivors with symptomatic RC suggest axes that could be trialed as both biomarkers and therapeutic targets." (PMID 41596217, 2026). "Interestingly, the sonicated extract inhibited the migration of prostate cancer cells via the downregulation of MMP-9 and upregulation of TIMP-1." (PMID 36605288, 2022). "Although these evidences suggest that ITGB5, TIMP1, and TMEM176B may work together to promote the invasion and metastasis of cancer cells, their molecular biological mechanisms in prostate cancer cells are still unclear and require further research." (PMID 34109215, 2021). "This miRNA has been shown to modulate metastasis in prostate cancer cell lines through the FOXP2 gene but not through TIMP-1." (PMID 30340564, 2018). "We found three groups of genes in the EMT differentially expressed list: a) known EMT genes (e.g. CDH1, ZEB1, TGFB, CDH2, VIM, TIMP1), b) EMT genes previously unknown in prostate cancer (LSR, S100A14, DPYSL3) and c) novel EMT genes (including C1orf116)." (PMID 28651527, 2017). "Nevertheless, circulating TIMP-1 levels in the blood do not seem to follow the same pattern of expression in the tissue and appear to be paradoxically up-regulated in prostate cancer patients instead (see more details in Section 3.1)." (PMID 24978435, 2014). "One should be cautious that it is the elevated levels of TIMP-1 in circulation that correlate with poorer prostate cancer prognosis, not necessarily corresponding tissue levels of TIMP-1 in tumor sites." (PMID 24978435, 2014). "Detection of TIMP-1 UEA α1, 2 fucosylation in prostate tissues was found to be superior to TIMP-1 protein in distinguishing aggressive and non-aggressive prostate cancer." (PMID 24015777, 2013). "In this study, we compared serum TIMP-1 levels in 140 prostate cancer patients in various disease stages and 16 males without known evidence of prostate cancer including patients with benign prostatic hyperplasia by sandwich ELISA." (PMID 24143225, 2013).
prostate carcinoma (continued). "To determine the potential role of TIMP-1 in prostate cancer progression, we selected three prostate cancer cells, PC3, 22RV1, and LAPC-4, because they are capable of forming tumors in immunocompromised mice, to overexpress v5-epitope tagged exogenous TIMP-1." (PMID 24143225, 2013). "Notably, S100A4 can promote invasive ability of prostate cancer cells through MMP9 and TIMP1 regulation." (PMID 23383075, 2013). "Our results showed that prostate cancer patients had an average serum TIMP-1 concentration of 351.4 ng/ml, significantly higher than the average concentration of 211.0 ng/ml seen in men without prostate cancer recruited from a urology clinic (p<0.001)." (PMID 24143225, 2013). "The data suggest that cytokine upregulation of TIMP-1 and coordinate downregulation of MMP-2 expression might control the molar ratio of TIMP-1 and MMP-2 to influence the level of protease activity and invasive behaviour of malignant prostate cancer cells." (PMID 12771930, 2003). "We found that TIMP-1 enhances ERK1/2 activity of serum starved prostate CAFs but not prostate cancer cells, suggesting that the in vivo effects of TIMP-1 on prostate cancer cells might be exerted through affecting prostate CAFs indirectly." (PMID 24143225, 2013). "Several are known biomarkers for diagnosis and prognosis of prostate cancer (APC, GSTP1, KIT, PYCARD, PGDGRB, RARB, RARRES1, and TIMP1) and some though not biomarkers, were found to be dysregulated in the disease (CDKN1B, MMP7, and MMP9)." (PMID 24626295, 2014). "Recently, our group reported that prostate cancer patients showed significantly elevated circulating TIMP-1 protein levels compared to men without cancer and that elevated plasma TIMP-1 levels predicted a poor survival in CRPC patients." (PMID 24978435, 2014). "Our results showed that expression of Snail, MMP-2 and MMP-9 but not Slug is up-regulated in the prostate cancer sections derived from PC3 and LAPC-4 cells overexpressing TIMP-1 when compared to the sections derived from the control PC3 and LAPC-4 cells." (PMID 24143225, 2013).
Myocardial fibrosis (53 papers, 2013 to 2026). "This study aimed to explore the effects of tissue inhibitor of metalloproteinases‐1 (TIMP‐1) on levocarnitine (LC)-mediated regulation of angiotensin II (AngII)-induced myocardial fibrosis (MF) and its underlying mechanisms." (PMID 36816804, 2023). "Fibrotic and extracellular remodeling markers Tgfβ1, Mmp2, Timp1, Col1a1, Col3a1, fibronectin and vimentin demonstrated a complex balance underlying myocardial fibrosis at different overload stages." (PMID 31181097, 2019). "Elevated plasma TIMP1 levels have been associated with myocardial fibrosis and used as a fibrosis biomarker in patients with heart disease." (PMID 30531796, 2018). "Since Gal-3 has been linked to myocardial fibrosis, it is plausible that elevated plasma concentrations of Gal-3 may also be linked to TIMP-1." (PMID 35004876, 2021). "TIMP1 promotes myocardial fibrosis through a novel mechanism involving CD63‐integrin β1 interaction, independent of its MMP‐inhibitory function." (PMID 41521401, 2026). "TIMP-1 also plays an active role in myocardial fibrosis and in the onset of pathological processes at an early stage, before the development of heart failure." (PMID 40095713, 2025). "The increased levels of TIMP-1 in tissues and plasma correlate with the degree of myocardial fibrosis and its diastolic dysfunction." (PMID 38540214, 2024). "These associations underscore the potential of TIMP-1 as a biomarker for disease severity and prognosis in DCM, reflecting both myocardial fibrosis and systemic disease burden." (PMID 39334904, 2024). "Increased levels of TIMP-1 in tissues and plasma correlate with the degree of myocardial fibrosis and its diastolic dysfunction." (PMID 37893149, 2023). "Previous in vitro experiments revealed that Wnt5a activates CFs and induces IL-6 and TIMP-1 synthesis, thereby promoting the occurrence of myocarditis and myocardial fibrosis." (PMID 36404310, 2022). "It has been demonstrated that TIMP-1 did contribute to ventricular remodeling and myocardial fibrosis in experimental HF models." (PMID 35004876, 2021). "The ultrastructure, degree of myocardial fibrosis, apoptosis index (AI), expression of microRNA-1, expression of microRNA-21, and mRNA of TIMP-1, MMP-9, BCL-2, and Bax of patients were compared and analyzed in each group." (PMID 34957910, 2021). "TIMP1 was shown to induce myocardial fibrosis through mediating an interaction between fibroblast membrane proteins, CD63, and integrin β1." (PMID 31141909, 2019). "Consistently, we observed upregulation of Timp1 in cardiomyocytes of Kdm3a-Tg mice as well as myocardial fibrosis in response to TAC, with most of the fibrotic genes being upregulated in cardiac fibroblasts." (PMID 30531796, 2018). "An increase in TIMP-1 expression to >1200 ng/mL indicates congestive heart failure and is closely related to the degree of myocardial fibrosis." (PMID 25861361, 2015). "Up-regulation of MMP9, MMP9/TIMP-1 ratio and down-regulation of TIMP-1 were more significant after neutralizing IL-22, associated with myocardial fibrosis exacerbation." (PMID 25547181, 2014). "Attenuate myocardial fibrosis and MMPs dysregulation by uppressing elevation of TIMP-1 and TGF-β." (PMID 40182630, 2025). "Importantly, TIMP1 is consistently upregulated in myocardial fibrosis during active remodeling phases." (PMID 41393260, 2025). "Furthermore, the extent of late gadolinium enhancement (LGE), which reflects myocardial fibrosis, was higher in the elevated TIMP-1 group (5.9% vs. 4.0%, p = 0.05)." (PMID 39334904, 2024). "TIMP-1 is consistently upregulated in myocardial fibrosis and is used as a marker of fibrosis." (PMID 37174632, 2023). "TIMP-1 has also been evaluated in studies as a biomarker of myocardial fibrosis." (PMID 37893149, 2023).
Myocardial fibrosis (continued). "Both collagens 1 and 3 are major myocardial fibrillar collagens, and it is well established that the tissue inhibitor of matrix metalloproteinase-1 (TIMP1) contributes to the collagen turnover and the remodeling of the ventricular extracellular matrix and that it promotes myocardial fibrosis." (PMID 35628236, 2022). "In this regard, in a rat diabetic model induced by STZ administration, a condition of myocardial fibrosis was related to a significant decrease in the expression of tissue inhibitor of metalloproteinase-1 (TIMP1) and MMP2 and an increase in the expression of MMP7, MMP11, MMP13 and MMP16." (PMID 34205197, 2021). "Interestingly, an opposite course with HCD was seen between the MMP2 and MMP9 collagen-degrading proteins and the profibrotic TIMP1, suggestive of increasing myocardial fibrosis." (PMID 34449561, 2021). "TIMP1 also promotes myocardial fibrosis in pressure overload." (PMID 34449561, 2021). "In the present cohort, TIMPs levels were significantly higher in patients with greater degrees of myocardial fibrosis (TIMP1), which could reflect changes in collagen homeostasis." (PMID 30413105, 2018). "In addition, our study demonstrated that the protein expression levels of MMP-9 and TIMP-1 were correlated with the levels of myocardial fibrosis in the LA with ageing and/or in AF." (PMID 23403858, 2013). "Of interest, a recent study has shown that TIMP1 deficiency have significantly reduced myocardial fibrosis via meditating an association between CD63 (cell surface receptor for TIMP1) and integrin β1 on CFs, leading to de novo collagen synthesis, reducing myocardial fibrosis, independent from MMPs." (PMID 40843168, 2025). "Consistently, Masson’s trichrome staining demonstrated a significant reduction in myocardial fibrosis after RDN, with lower expression of fibrosis-related genes including Col1a2, Timp1, Fn1 and α-SMA." (PMID 40958035, 2025). "The decline in cardiac function in HFpEF mice was also accompanied by a significant increase in the mRNA expression levels of Bnp and genes related to myocardial fibrosis, such as α-SMA, Fn1, Col1a2, and Timp1." (PMID 38402404, 2024). "TIMP-1 can specifically inhibit the activity of MMP-9 and alleviate the degradation of extracellular matrix collagen, thus improving myocardial fibrosis." (PMID 36820397, 2023). "With the progression from AVMC to DCM, the severity of myocardial fibrosis significantly increased accompanied by up-regulation of COL1-A1, COLA3-A1, MMP9 and ratio of MMP9/TIMP-1 but down-regulation of TIMP-1." (PMID 25547181, 2014). "In addition, myocardial fibrosis in mdx mice began with the increase of CTGF expression, and the upregulation of CTGF was consistent with the increase of TIMP-1 expression." (PMID 34221074, 2021). "In addition, JMJD1A has been confirmed to activate TIMP1 and secrete it into the ECM of cardiomyocytes, thereby promoting myocardial fibrosis." (PMID 35186975, 2021). "KDM3A-activated TIMP1 in cardiomyocytes may be secreted into the ECM, subsequently activating resident cardiac fibroblasts and leading to myocardial fibrosis." (PMID 30531796, 2018). "Through CD63 (TIMP1 cell-surface receptors), TIMP1 and integrin beta 1 could promote activation and nuclear transfer of Smad2/3 and the beta serial protein, resulting in the deposition of types I and III collagen and subsequently myocardial fibrosis." (PMID 38728374, 2024). "In the process of myocardial fibrosis induced by pressure load, a decrease in MMP-1 expression can prevent ventricular expansion, protect heart function, and increase the myocardial MMP 1/TIMP-1 ratio, which is an effective strategy to prevent hypertensive heart disease." (PMID 25861361, 2015). "Taking into account the assessment of myocardial fibrosis markers, there were no significant changes in the concentration of matrix metallopeptidase 9 (MMP-9) and tissue inhibitors of metalloproteinases 1 (TIMP-1) in the study group." (PMID 38928407, 2024).